PRDM16 (PR/SET domain 16)
Diseases named in the same sentence as PRDM16 in open-access papers (continued):
Sharing a sentence is not in itself a finding about the gene and the disease.
Obesity (continued). "Consequently, directly targeting PRDM16 proteins in thermogenic adipose tissue emerges as a potential strategy for combating obesity and related metabolic disorders." (PMID 39351529, 2024). "To investigate the anti-obesity mechanism of PD, we examined the expression of thermogenic proteins PRDM16 and UCP1, mitochondrial biosynthesis-related protein PGC-1α, TFAM and cAMP pathway related protein P-CREB in adipose tissue after (20R)-panaxadiol administration." (PMID 36909162, 2023). "Collectively PRDM16 is a viable target to treat obesity and diabetes." (PMID 37211698, 2023). "In addition, adipocyte-specific deletion of PRDM16 inhibited beige adipocyte function in subcutaneous fat and promoted obesity, as well as aggravated insulin resistance and hepatic steatosis in mice under HFD, while caused minimal effects on brown fat." (PMID 36841479, 2023). "Importantly, extended PRDM16 protein stability by adipocyte-specific deletion of CUL2–APPBP2 counteracted diet-induced obesity, glucose intolerance, insulin resistance and dyslipidaemia in mice." (PMID 35978186, 2022). "In addition, some well-known drugs alleviate obesity and diabetes by regulating PRDM16-related signaling pathways." (PMID 35462933, 2022). "This evidence suggests that the PRDM16 protein may be a promising therapeutic target for obesity and diabetes." (PMID 35462933, 2022). "In addition, pregnancy obesity decreases PRDM16 expression, oxidative metabolism, and mitochondrial biogenesis in the placenta." (PMID 36093083, 2022). "In this review, we summarize the evidence of PRDM16 involvement in the progression of obesity and diabetes and that PRDM16 may be a promising therapy for obesity and diabetes." (PMID 35462933, 2022). "Prdm16 enhances the Ucp-1-mediated thermogenic gene programming in subcutaneous white adipose, promoting energy expenditure and improving metabolism, which resists obesity." (PMID 36422269, 2022). "Multiple experimental data suggest that stimulating or stabilizing PRDM16 expression and inducing PRDM16 function may be a potential way to treat obesity and diabetes." (PMID 35462933, 2022). "Hence, UCP1-deficient mice also possess a positive metabolic phenotype indicating that beige fat biogenesis driven by adipose-specific overexpression of PRDM16 protects from cold-induced hypothermia, diet-induced obesity, and glucose intolerance." (PMID 34367068, 2021). "Mstn-/- and Adipo-PRDM16 KO; Mstn-/- were also equally and significantly protected from hepatic steatosis, in accordance with prior studies examining the consequences of myostatin deletion in obesity models." (PMID 33220490, 2021). "Since the “browning” of white fat is important in pig in terms of producing heat fighting against cold environment, avoiding obesity, and improving meat quality, understanding the critical role that PRDM16 gene played in pig adipose “browning” and energy metabolism is of great significance." (PMID 31312653, 2019). "We found that CA promotes activation of BAT function and differentiation by upregulation of genes related to BAT thermogenesis, mitochondrial biogenesis and mitochondrial activation such as Pgc1a, Ucp1, Prdm16, Sirt3, Cidea and CytC, thereby suppress obesity by promoting EE." (PMID 31443565, 2019). "Adipocyte-specific deletion of PRDM16 inhibited the induction of thermogenic activity in brite adipocytes following treated by cold exposure or β3 adrenergic agonist, and HFD-fed PRDM16-deficient mice tended to develop obesity." (PMID 27835589, 2016). "This study not only support the roles of co-stimulation of β3-adrenergic and PPARα receptors on the induction of white-to-brown adipocyte phenotypes, but also set the place for the utility of new regulators such as PRDM16 for the development of new therapeutics of complicated obesity." (PMID 24159189, 2014).
Obesity (continued). "Therefore, the induction of Prdm16 by exercise could help to promote BAT recruitment and prevent the loss of brown fat characteristics that occurs during obesity and aging, as recently reported by our group." (PMID 37204588, 2023). "Furthermore, miR‐34a has been found to be increased which is associated with obesity and inhibit fat cell browning; Downregulation of miR‐34a can elevate expression of FGF21 and results in induction of the browning genes Ucp1, Pgc‐1, and Prdm16." (PMID 36062491, 2022). "However, DNA demethylation of CpG islands in the Prdm16 promoter, likely mediated by TET proteins, is required for its expression, by which demethylation of the Prdm16 promoter improves brown/beige adipogenic capacity and alleviates obesity in aged mice challenged with high-fat diet." (PMID 35371604, 2022). "It is speculated that PRDM16 protein could be an effective way to treat obesity and diabetes." (PMID 35462933, 2022). "Therefore, PRDM16, UCP1, CIDE-A, and COX1 gene expression can be a key strategy to reduce metabolic disorders caused by obesity because brown fat can increase energy consumption and protect against obesity through a specialized energy-burning program." (PMID 36093083, 2022). "As a result, the aim of this study was to investigate the role of PRDM16 in the differentiation of pig white adipocyte and energy metabolism, which may provide some new insight in the way of fighting with obesity and improving the living number of newborn piglets." (PMID 31312653, 2019). "Thus, we speculate that combining β3 adrenergic pathway and PRDM16 pathway would be an effective strategy to counteract obesity." (PMID 28481288, 2017). "Two imprinted genes, namely GABRB3 and PRDM16, also showed differential methylation in both OBS and ALSPAC cohorts in male offspring from mothers with obesity." (PMID 35500004, 2022). "Studies have shown that PRDM16 and its related coregulatory factors PGC-1α and CTBP1/2 are potential targets for obesity-related therapy, controlling WAT-to-BAT conversion." (PMID 35462933, 2022). "Notably, PRDM16: rs2651899 variant that conferred the strongest association with obesity (cOR = 44.60, 95% CI: 11.60–172.02, P = 0.0001), has not been associated with obesity in any non-Arab ethnic population." (PMID 34131278, 2021). "This suggests that by decreasing the expression of Pgc-1α, Prdm16 and Cidea, DBP exposure reduced the levels of UCP1 and lipid degradation and accelerated the accumulation of fat, thus resulting in obesity." (PMID 33004990, 2020). "Mice overexpressing Prdm16 in fat tissue had marked increases of browning in WAT, specifically subcutaneous depots, resulting in protection from diet-induced obesity and glucose intolerance." (PMID 28677104, 2018). "At least 4/15 genes containing ≥6 differentially methylated CpG sites had a potential role in obesity and/or related traits (PRKCZ, PRDM16, FOXP2, THBS1)." (PMID 25651499, 2015). "In brown adipose tissue, METTL3 deletion decreases the m6A modification and expression of the PR domain containing 16 (PRDM16), uncoupling protein 1 (UCP-1), and peroxisome proliferator-activated receptor gamma (PPARG) and thereby promotes high-fat diet-induced obesity." (PMID 38560499, 2024). "Moreover, it upregulated the expression of brown fat markers including PR domain containing 16 (PRDM16), uncoupling protein 1 (UCP1), and PPARγ coactivator-1 (PGC-1α), which reduced obesity and restored metabolic homeostasis by altering brown fat phenotype." (PMID 35082907, 2022). "Thus, NHDC and GNHDC exerted an anti-obesity effect by increasing fat browning through the regulation of AMPK targets such as PGC-1 α, PRDM16, and UCP1." (PMID 35268062, 2022). "Obesity increased the abundance of C/EBP-α, C/EBP-β, and PPAR-γ, whereas PRDM16 was decreased." (PMID 32230849, 2020).
Obesity (continued). "Transgenic expression or deletion of PR domain containing 16 (PRDM16) in WAT, a transcription coregulator for brown adipocyte development, could bi-directionally attenuate diet-induced obesity (DIO) or lead to obesity." (PMID 33372630, 2020). "Notably, adipocyte-specific deletion of PRDM16 leads to the absence of functional beige adipocytes, concomitant with hepatic steatosis, as another complication of obesity." (PMID 34367068, 2021). "In order to evaluate the effect of obesity and exercise training on adipocyte differentiation, protein abundance of biomarkers involved in the adipogenesis was measured, including C/EBP-α, C/EBP-β, PPAR-γ, and a master transcription factor regulating brown adipogenesis PRDM-16." (PMID 32230849, 2020). "We report here that Hlx, at least in part through Prdm16-mediated co-activation, directly drives a full program of thermogenesis and a robust WAT to brown-like fat switch, which in turn improves glucose homeostasis and prevents both genetic and high-fat diet-induced obesity and fatty liver." (PMID 28701693, 2017). "Dietary addition of capsaicin promoted WAT browning to fight obesity but did not prevent obesity in TRPV1−/− mice, suggesting that activation of the TRPV1 pathway promotes the interaction between PPARγ and PRDM16 protein to protect against obesity." (PMID 35462933, 2022). "The most likely explanation for enhanced beige adipocytes in scWAT is trans-differentiation of WAT, as illustrated by the marked downregulation of C/EBPα and C/EBPβ and upregulation of PRDM16 and PPAR-γ, thereby overcoming the negative effects of obesity." (PMID 32230849, 2020). "For example, transgenic expression of PRDM-16 in WAT promoted the development of beige adipose tissue and resistance to obesity without enhancing the BAT mass." (PMID 28804438, 2017). "Furthermore, in mice that lack PRDM-16 in the adipose tissues, CAP fails to prevent HFD-induced obesity." (PMID 39204203, 2024).
migraine (24 papers, 2012 to 2025). "Our study detected a significant influence of the PRDM16 rs2651899 on the risk of overall migraine and MA." (PMID 35454329, 2022). "Main effect analysis indicated that intergenic polymorphism rs77864828, and with smaller relevance, intron variant rs2455107 in PRDM16 represent genetic factors for common migraine." (PMID 34972135, 2021). "In summary, main effect analyses including regression models and neural network based predictive power calculations indicated that rs2455107 of PRDM16 and intergenic rs11209657, rs77864828 of 1p31.1 are potential candidate polymorphisms behind migraine." (PMID 34972135, 2021). "We further found the pathways “positive regulation of cytosolic calcium ion concentration” and “inositol phosphate-mediated signaling” and hub genes including MEF2D, TSPAN2, PHACTR1, TRPM8 and PRDM16 related to migraine susceptibility." (PMID 32046629, 2020). "Association of the PRDM16 gene to migraine has been confirmed in several replication studies and meta-analyses and it is now considered a well-established migraine candidate gene." (PMID 30382894, 2018). "They found a nominal association of four SNPs with migraine with aura: rs2651899 (within the PR domain containing 16 [PRDM16] gene), rs10166942 (near TRPM8), rs12134493 and rs10504861." (PMID 26231841, 2015). "Three markers have shown a consistent association in independent cohorts of patients with migraine: rs2651899 in the PRDM16 gene, rs10166942 in theTRPM8 gene, and rs11172113 in the LRP1 gene." (PMID 25705201, 2015). "Recently, a GWA study identified the SNPs in the PRDM16 gene as a susceptibility loci for the common migraine in the general population." (PMID 24863034, 2014). "Our main effect analysis for migraine demonstrated only 6 nominally significant SNPs, and among them only one could be associated with a gene, the intron region of PRDM16: rs2455107." (PMID 34972135, 2021). "In this context, it is noted that polymorphisms in genes including TGFBR2, TSPAN2, and PRDM16 are also associated with migraine risk, underlining a potentially important role of these genes in migraine pathogenesis and therapy success in migraine." (PMID 35222013, 2021). "At the same time, different variants of PRDM16 associated with migraine in several earlier studies." (PMID 34972135, 2021). "Nonetheless, previous and current results indicate that polymorphisms of PRDM16 may be consistent and relevant candidates for migraine susceptibility." (PMID 34972135, 2021). "We have previously replicated the finding of an association for two of the established risk alleles for migraine in a Swedish migraine case-control population, rs2651899 in PRDM16 (PR/SET domain 16) and rs1835740 located between MTDH (metadherin) and PGCP (carboxypeptidase Q) on chromosome 8q22.1." (PMID 30382894, 2018). "The common variant in the PRDM16 gene has been associated with migraine in European, Chinese, and North Indian populations, but the role of this gene in migraine is unknown." (PMID 25705201, 2015). "Migraine‐related genes (e.g., CALCA, PRDM16) show a moderate association (OR = 1.85, 95% CI [1.05–3.24]), suggesting a genetic influence on triptan response beyond pain pathways." (PMID 41121943, 2025). "A genome-wide association study (GWAS) migraine SNP, rs2651899, located in the PR/SET Domain 16 (PRDM16) gene, was associated with triptan response in a Danish migraine cohort." (PMID 38634984, 2024). "In our study, substantially elevated SNP-based heritability and replicable top hits in risk loci of PRDM16, FHL5, ASTN2, STAT6/LRP1, SLC24A3 genes were found among migraine-first patients." (PMID 39333847, 2024). "A subsequent Chinese replication study of 581 migraine cases and 533 ethnically matched controls identified three risk loci rs2274316 (MEF2D), rs6478241 (ASTN2) and rs2651899 (PRDM16) previously identified in European samples." (PMID 37245199, 2023).
migraine (continued). "In summary, analyses presented in this paper validate polymorphisms in p31.1 region of chromosome 1, PRDM16, ADGRL2, REST and HPSE2 genes in migraine." (PMID 34972135, 2021). "Of note, a polymorphic expression of PRDM16 has been, together with MMP16, also linked to modulated therapy success with anticonvulsants in migraine." (PMID 35222013, 2021). "Genetic variants in genes such as SLC6A4 (SERT), DRD2 (dopamine receptor), PRDM16 or CYP1A2, and GNB3 have been associated with a modified therapy outcome with triptans in migraine and cluster headache, respectively." (PMID 35222013, 2021). "Earlier GWAS identified migraine susceptibility SNPs nearby genes with mainly putative or known neuronal functions, including MTDH, PRDM16, TPRM8 and LRP1." (PMID 31226929, 2019). "Rs2651899 is located in the gene PRDM16 (PR domain containing 16), a zinc finger transcription factor whose potential role in migraine is unclear." (PMID 24674449, 2014). "Metabolic syndrome, common migraine, and facial morphology were related to muscle metabolism by SNPs in the PRDM16 gene." (PMID 24863034, 2014). "Moderate associations were observed for migraine susceptibility genes, including CALCA and PRDM16 (pooled OR = 1.8), implying that genetic predisposition may also affect pharmacological efficacy." (PMID 41121943, 2025). "In conclusion, based on our findings the PRDM16 rs2651899 is associated with migraine and MA, and the rs10166942 (near the TRPM8 gene) CT genotype is associated with increased migraine risk and MO risk, while the homozygosities appear to confer a protective effect." (PMID 35454329, 2022). "In this meta-analysis, we investigated the effect of three variants (namely the PRDM16 rs2651899, the rs10166942 near the TRPM8 gene, and the LPR1 rs11172113) on the risk of migraine, as well as on the risk of the main migraine phenotypes, namely the MA and the MO." (PMID 35454329, 2022). "Furthermore, results allowed the separation of variants that play a role in migraine accompanied by depression, like ADGRL2, REST and HPSE2, from those that play a general role in migraine, like PRDM16." (PMID 34972135, 2021). "Rs2651899 of PRDM16 showed associations in the Women’s Genome Health Study (WGHS) with migraine compared to non-migraineurs and also with migraine compared to non-migraine type headache." (PMID 34972135, 2021). "Moreover, aberrant PRDM16 expression has now been linked to (cardio)vascular diseases, including left ventricular non-compaction, migraine, and coronary artery disease." (PMID 40439125, 2025). "The precise mechanism by which PRDM16 may be involved in migraine remains unknown." (PMID 35454329, 2022). "How PRDM16 might contribute to migraine pathology remains to be elucidated." (PMID 24674449, 2014). "Multiple GWAS studies have proposed genes (PRDM16, TRPM8 or LRP1) and locus (Chr8q22.1) to be involved in the migraine." (PMID 24974787, 2015). "However, the 2016 finding by no means suggests that a neuronal origin of migraine is now excluded, already because at least five genes (PRDM16, MEF2D, FHL5, ASTN2, LRP1) (also) have a neuronal function." (PMID 30634909, 2019).